PIK3CA (phosphatidylinositol-4,5-bisphosphate 3-kinase catalytic subunit alpha)
Diseases named in the same sentence as PIK3CA in open-access papers (continued):
Sharing a sentence is not in itself a finding about the gene and the disease.
goblet cell adenocarcinomas (1 paper, 2023). "Mutations and inactivation of the PTEN gene frequently occur in numerous tumors, including well-differentiated neuroendocrine tumors of the appendix and appendiceal goblet cell adenocarcinoma, sometimes in association with activating mutations in the PIK3CA gene." (PMID 37509254, 2023).
Gorham-Stout syndrome (1 paper, 2023). "LMs may appear as part of a syndrome, including generalised lymphatic anomaly, central conducting lymphatic anomaly, Gorham-Stout syndrome, kaposiform lymphangiomatosis, and other diseases associated with PIK3CA mutation, such as PIK3CA-related overgrowth syndrome (PROS)." (PMID 37115326, 2023).
Hepatic steatosis (1 paper, 2019). Steatosis is a term used to denote lipid accumulation within hepatocytes. "Previously, we showed that activated mutant forms of PIK3CA alone induce hepatic steatosis when overexpressed in the mouse liver." (PMID 30975125, 2019). "Altogether, the results demonstrate that loss of SGK3 does not affect activated H1047R or E545K PIK3CA mutants induced hepatic steatosis in mice and lipogenesis in HCC cell lines." (PMID 30975125, 2019). "To determine whether SGK3 is required for activated PIK3CA mutant induced hepatic steatosis in vivo, we hydrodynamically transfected PIK3CA(H1047R) and PIK3CA(E545K) constructs, which we will refer here to as H1047R and E545K, into the Sgk3+/+ or Sgk3−/− mouse liver." (PMID 30975125, 2019).
hereditary cancer syndromes (1 paper, 2025). "In addition, the presence of hereditary cancer syndromes, PIK3CA or ESR1 mutations, and PD-L1 expression status were indicated." (PMID 41278370, 2025).
hidradenocarcinoma (1 paper, 2012). A carcinoma with apocrine and less often eccrine differentiation, arising from the sweat glands. "Activating PIK3CA mutations were detected in 1 hidradenocarcinoma (c.1624G>A; p.Glu542Lys) and 2 porocarcinomas (c.1624G>A; p.Glu542Lys and c.1633G>A; p.Glu545Lys)." (PMID 23056620, 2012).
hydrocele (1 paper, 2024). "The third PIK3CA variant, p.Glu542Lys, has been reported in an 8-month-old male patient exhibiting bilateral hydrocele, lipomatous infiltration in muscles and internal structures, vascular malformations, kidney abnormalities, and significant delays in gross motor development." (PMID 39872006, 2024).
Hyperinsulinemia (1 paper, 2021). An increased concentration of insulin in the blood. "However, since PIK3CA is ubiquitously expressed in diverse types of tissues, including insulin-responsive tissues, the use of this inhibitor could elicit hyperinsulinemia and diabetes." (PMID 35578699, 2021).
Hypertension (1 paper, 2025). The presence of chronic increased pressure in the systemic arterial system. "Network pharmacology identified ten key bioactive compounds (e.g., liquiritigenin, isoliquiritigenin, and caffeic acid), 149 hypertension-related targets, and ten core targets such as SRC, PIK3CA, PIK3CB, EGFR, and IGF1R." (PMID 41155608, 2025).
Impaired glucose tolerance (1 paper, 2013). An abnormal resistance to glucose, i.e., a reduction in the ability to maintain glucose levels in the blood stream within normal limits following oral or intravenous administration of glucose. "Mice with hepatic knockout of Pik3ca showed reduced insulin sensitivity, impaired glucose tolerance, and increased gluconeogenesis." (PMID 23826284, 2013). "PIK3CA is critical in the insulin transduction pathway and dysfunction of PIK3CA may lead to IR and impaired glucose tolerance, as suggested by evidence from the hepatic Pik3ca knockout mice." (PMID 23826284, 2013).
infantile spasms (1 paper, 2019). A rare epilepsy syndrome characterized by onset of epileptic spasms in infants between 2 and 12 months of age, and rarely up to 24 months. "A smaller fraction of panel-positive FCD2/HME cases (7/34) with somatic variants in MTOR, PIK3CA, or TSC2 also presented infantile spasms." (PMID 31444548, 2019).
Infertility (1 paper, 2026). "Screening via the STRING platform and Cytoscape 3.10.1 software yielded four core targets for ATBC-induced infertility-HSP90AA1, PIK3CA, CASP3, HRAS-and four core targets for icariin treatment-IL6, TNF, STAT3, and INS." (PMID 41898778, 2026).
intestinal tumors (1 paper, 2025). "We developed genetically engineered mouse models with mutant Pik3ca that form primary intestinal tumors within 3 months, with a subset progressing to liver metastasis, overcoming the limitations of previous models." (PMID 39808497, 2025). "Our study presents a transgenic mouse model that develops primary intestinal tumors and metastasizes to the liver within an intact immune system, driven by a single oncogenic event, Pik3ca, in combination with AOM treatment." (PMID 39808497, 2025).
ischemia (1 paper, 2022). A hypoperfusion of the BLOOD through an organ or tissue caused by a PATHOLOGIC CONSTRICTION or obstruction of its BLOOD VESSELS, or an absence of BLOOD CIRCULATION. "There were 10 active constituents against ICVD, including quercetin, luteolin, kaempferol, and naringenin, and 10 important targets for anticerebral ischemia, namely, PIK3CA, APP, PIK3R1, MAPK1, MAPK3, AKT1, PRKCD, Fyn, RAC1, and NF-κB1." (PMID 35432563, 2022).
keloid (1 paper, 2020). An irregularly shaped, elevated mark on the skin caused by deposits of excessive amounts of collagen during wound healing. "The results of qPCR showed that, compared to the control group, mRNA levels of PIK3CA, Akt1, and mTOR were significantly increased in keloid fibroblasts from the IGF-1-treated group (P < 0.05)." (PMID 33062677, 2020). "Compared to the control and Wubeizi ointment treated-group, mRNA levels of PIK3CA were significantly increased in keloid fibroblasts from the IGF-1+Wubeizi ointment-treated group and IGF-1-treated group (P < 0.05)." (PMID 33062677, 2020).
Langerhans cell histiocytosis (1 paper, 2024). Langerhans cell histiocytosis (LCH) is a systemic disease associated with the proliferation and accumulation (usually in granulomas) of Langerhans cells in various tissues. "Non-Langerhans cell histiocytosis shares a high incidence similar to that of BRAF V600E mutations, along with genetic alterations in ARAF, MAP2K1, PIK3CA, K/NRAS, and gene fusions involving BRAF, ALK, NTRK1, and ETV3-NCOA2." (PMID 38963520, 2024).
laryngeal tumors (1 paper, 2020).
leprosy (1 paper, 2018). Leprosy is a chronic infectious disease affecting primarily the skin and peripheral nervous system. "In contrast, PIK3CA miRNAs were downregulated in all forms of leprosy in comparison to HS, and AKT1 miRNAs was more prominent in LL patient lesions." (PMID 29593724, 2018).
low grade glioma (1 paper, 2024). A grade I or grade II glioma arising from the central nervous system.
lung disease (1 paper, 2023). "Notably, we observed an elevated occurrence of the ERBB2 p.Pro1170Ala variant in oligometastatic lung disease, and an absence of PIK3CA mutations in oligometastatic liver and lung disease." (PMID 37858132, 2023).
lung neoplasm (1 paper, 2021). A benign or malignant, primary or metastatic neoplasm involving the lungs.
lung neuroendocrine tumours (1 paper, 2012). "Notably, the high-grade LCNECs demonstrated an unexpected lower frequency of PIK3CA gene mutations (11.8%) compared with the other types of lung neuroendocrine tumours." (PMID 22949056, 2012). "To assess the frequency of PIK3CA gene mutations in BP-NETs we sequenced genomic DNA isolated from formalin-fixed and paraffin-embedded tissues in a large series of lung neuroendocrine tumours, including 75 low-grade TCs, 23 intermediate-grade ACs, 17 high-grade LCNECs and 75 high-grade SCLCs." (PMID 22949056, 2012).
lymph node tumor (1 paper, 2010). "On the other hand, if the PIK3CA/KRAS ratio were the same in the primary and lymph node tumor, then the PIK3CA mutation frequency would have been .08, which is still detectable with this technology." (PMID 20233444, 2010). "In sample 0940, the KRAS/PIK3CA mutation decreased by almost 1/2 in the lymph node tumor compared to the primary." (PMID 20233444, 2010).
lymphangiectasia (1 paper, 2026). "They cause lymphangiectasia through overactivation of the cell signaling pathway, such as phosphatidylinositol-4,5-bisphosphate 3-kinase catalytic subunit alpha (PIK3CA) pathway and RAS-MEK, and the lymphangiectasia contacting the skeleton progressively lyses the bone and leads to bone loss." (PMID 41554698, 2026).
lymphangioma (1 paper, 2024). A benign lesion composed of dilated lymphatic channels. "Similarly, analysis of DNA extracted from the affected lymphangioma tissues identified the same PIK3CA p.Glu542Lys pathogenic variant, with a VAF of 7% at a sequencing depth of 1377x in one sample, and a VAF of 9% at a sequencing depth of 1,144x in the other sample." (PMID 39872006, 2024).
lymphatic disorders (1 paper, 2021). "Mutation of c.1633G > A in PIK3CA has been reported as a disease-causing mutation associated with lymphatic disorders." (PMID 33964933, 2021).
lymphoid neoplasm (1 paper, 2014). A neoplasm composed of a lymphocytic cell population which is usually malignant (clonal) by molecular genetic and/or immunophenotypic analysis. "Altogether, these results suggest that PIK3CA mutations are not a frequent AKT activating mechanism in lymphoid neoplasm." (PMID 25096023, 2014).
lymphopenia (1 paper, 2025). Reduction in the number of lymphocytes. "Here, we present a patient with a pathogenic PIK3CA variant who developed prolonged severe neonatal lymphopenia in the context of viral sepsis and peritonitis." (PMID 41357804, 2025).
malignant mesothelioma (1 paper, 2021). A malignant neoplasm of the pleura or peritoneum, arising from mesothelial cells. "In the patient with a confirmed PR, the tumor did not harbor a PIK3CA mutation or PTEN loss but an alteration in the BAP1 gene (exon 3 p.D34fs), a potent tumor suppressor implicated in PI3K signaling pathway and in the pathogenesis of malignant mesothelioma, was found." (PMID 33660194, 2021).
metastatic prostate carcinoma (1 paper, 2025). A carcinoma that arises from the prostate gland and has spread to other anatomic sites. "Key predictors of metastatic prostate cancer identified were T stage, GS, PIK3CA, LRP6, LRRK2, and APOBEC3B deletion." (PMID 40660132, 2025). "Several gene mutations, including PIK3CA, LRP6, LRRK2, and BRCA2, were found to be associated with metastatic prostate cancer and BCR." (PMID 40660132, 2025). "Subsequently, the multivariate analysis, focusing on these previously identified significant factors, confirmed T stage, GS, LRP6, LRRK2, PIK3CA, and APOBEC3B deletion as significant predictors of metastatic prostate cancer." (PMID 40660132, 2025).
multiple sclerosis (1 paper, 2025). A progressive autoimmune disorder affecting the central nervous system resulting in demyelination. "Recent studies have shown that the expression of PIK3CA (Phosphatidylinositol-4, 5-bisphosphate 3-kinase catalytic subunit alpha) is upregulated in patients with multiple sclerosis." (PMID 38886317, 2025). "The significant upregulation of PIK3CA might be a disease signal that is related to iron death pathways and plays a crucial role in the onset and progression of multiple sclerosis." (PMID 38886317, 2025). "For patients with multiple sclerosis, treatments targeting PIK3CA might be more effective." (PMID 38886317, 2025).
myxoma (1 paper, 2025). A benign soft tissue neoplasm characterized by the presence of spindle and stellate cells, lobulated growth pattern, and myxoid stroma formation. "While PRKAR1A, PIK3CA (Q546E) and KRAS mutation (G12V), mutations have been detected in a minority of OMs and GNAS1 mutations are well described in intramuscular myxomas, neither has emerged as a consistent molecular feature of OMs." (PMID 41364259, 2025).
necrotizing enterocolitis (1 paper, 2024). Necrotizing enterocolitis (NEC) is a devastating disease that affects mostly the intestine of premature infants. "In this report, we present a unique clinical presentation of a PIK3CA mutation associated with necrotizing enterocolitis (NEC), which has not been previously reported." (PMID 38813336, 2024).
neural tumors (1 paper, 2024).
osteoporosis (1 paper, 2025). A condition of reduced bone mass, with decreased cortical thickness and a decrease in the number and size of the trabeculae of cancellous bone (but normal chemical composition), resulting in increased fracture incidence. "Both molecular docking and Western blotting experiments showed that the anti‐osteoporosis effects of GA‐A were generated through the upregulation of PIK3CA protein expression." (PMID 40236832, 2025). "In order to verify this conjecture, we used bioinformatics to screen the targets of Ganoderic acid A on osteoporosis and identified PIK3CA as the main target of GA‐A against osteoporosis." (PMID 40236832, 2025). "Previous studies have found that in glucocorticoid‐induced osteoporosis, icariin can activate PIK3CA, thereby inhibiting osteoporosis." (PMID 40236832, 2025). "Ganoderic acid A might play an important role in the prevention of osteoporosis by modulating the PIK3CA/p‐Akt/TWIST1 signaling pathway." (PMID 40236832, 2025). "According to the relevant literature, the effects of AR and CTNNB1 have already been studied well in the related studies, while the effects of PIK3CA still remain unclear in osteoporosis." (PMID 40236832, 2025). "Whether PIK3CA, as a target of GA‐A against osteoporosis, can also be involved in the inhibition of osteoclast formation needs further investigation." (PMID 40236832, 2025). "Therefore, PIK3CA was selected for the subsequent mechanistic study for GA‐A against osteoporosis." (PMID 40236832, 2025). "PIK3CA might be a target for the prevention and treatment of osteoporosis." (PMID 40236832, 2025). "Therefore, it is reasonable to speculate that Ganoderic acid A can promote bone formation in osteoblasts by activating PIK3CA to catalyze the PI3K/Akt signaling pathway and then inhibiting the protein expression of TWIST1, thus playing a positive role in preventing and treating osteoporosis." (PMID 40236832, 2025).
Ovarian cyst (1 paper, 2019). The presence of one or more cysts of the ovary. "Remarkably, the ovarian cyst also had a second likely pathogenic variant in PIK3CA, c.2135 T>C (p.(Leu712Pro), VAF <10%), and a third likely pathogenic variant in CDKN1C, c.167A>G (p.(Glu56Gly), VAF 36%–45%)." (PMID 30761771, 2019). "In one individual, three distinct P/LP variants were observed, including two co‐occurring PIK3CA variants in an ovarian cyst." (PMID 30761771, 2019).
ovarian cystadenoma (1 paper, 2022). A benign ovarian surface epithelial-stromal tumor characterized by the presence of cystic structures lined by serous epithelial cells, mucinous columnar epithelial cells, or endometrial-type well-differentiated cells. "Thus, we generated immortalized epithelial cells from ovarian cystadenoma cells and introduced oncogenic KRAS, PIK3CA, and KRAS + PIK3CA mutations, which appeared to be the most essential for developing LGSOCs." (PMID 35326657, 2022).
ovarian mucinous cystadenoma (1 paper, 2024). "We were not able to determine if the PIK3CA variant identified by CancerSEEK originated from the ovarian mucinous cystadenoma." (PMID 39512764, 2024).
Paget disease (1 paper, 2013). A malignant neoplasm composed of large cells with large nuclei, prominent nucleoli, and abundant pale cytoplasm (Paget cells). "Our previous study showed that DLC-1 methylation significantly correlated with PIK3CA mutations in Paget's disease." (PMID 23509688, 2013).
papillary carcinomas of the breast (1 paper, 2023). "AKT1 and PIK3CA gene alterations, which are typically found in papillary carcinomas of the breast, were also not found." (PMID 37754277, 2023).
parathyroid adenomas (1 paper, 2020). "The most intriguing feature of the identified PIK3CA mutations is that, in all four parathyroid adenomas, observed PIK3CA mutations were subclonal and likely present in only a subpopulation of tumor cells." (PMID 32537547, 2020). "We analyzed a series of 391 parathyroid neoplasia samples for mutations in PIK3CA mutational hotspots and identified mutations in four typically presenting sporadic parathyroid adenomas." (PMID 32537547, 2020). "We identified activating PIK3CA hotspot mutations in four parathyroid adenomas (1%)." (PMID 32537547, 2020). "Four parathyroid adenomas (1%) had subclonal, somatic, heterozygous, activating PIK3CA mutations." (PMID 32537547, 2020). "In the present study, we explored the role of specific PIK3CA gain‐of‐function mutations in a large series of typical, benign sporadic parathyroid adenomas to assess the potential specificity of such mutations for malignant, as opposed to benign, parathyroid tumors." (PMID 32537547, 2020). "With this mounting evidence for the contribution of PIK3CA activating variants to parathyroid neoplasia, we set out to assess if such mutations are present in parathyroid adenomas and to thus evaluate their potential specificity for malignant parathyroid disease." (PMID 32537547, 2020). "To assess the potential specificity for malignant, as opposed to benign parathyroid disease, of PIK3CA hotspot mutations, we PCR‐amplified and Sanger sequenced codons 111, 542/545, and 1047 and the immediate flanking regions in genomic DNA from 391 typical, sporadic parathyroid adenomas." (PMID 32537547, 2020).
parotid carcinoma (1 paper, 2016). "The PIK3CA mutation (H1047R) in the parotid carcinoma patient was validated with Sanger sequencing." (PMID 27105424, 2016).
perineurioma (1 paper, 2021). A usually benign perineurioma not associated with a nerve, arising from the soft tissues. "In two patients (5%), CTS occurred due to a benign tumor (n = 2 perineurioma), of which one perineurioma was associated with a PIK3CA gene mutation." (PMID 34438514, 2021).
pineocytoma (1 paper, 2025). "CNS_016, initially diagnosed as pineocytoma, harboured pathogenic mutations in FGFR1 and PIK3CA, alterations frequently reported in this tumour type." (PMID 41033792, 2025).
pneumonia (1 paper, 2022). An acute, acute and chronic, or chronic inflammation focally or diffusely affecting the lung parenchyma, caused by an infection in one or both of the lungs (by bacteria, viruses, fungi, or mycoplasma.). "Compared with the model group, isorhamnetin reduced the protein expressions of SYK, IL-6, MAPK14, MAPK8, TNF-α, AKT, p-Akt, PIK3CA, EGFR and IL-1β in lung tissues of pneumonia mice." (PMID 36506534, 2022).